CCNB1 (cyclin B1)
Diseases named in the same sentence as CCNB1 in open-access papers (continued):
Sharing a sentence is not in itself a finding about the gene and the disease.
cancer (continued). "Since upregulation of RGC-32 expression has been linked to numerous cancers, potentially through the role of RGC-32 as an activator of the mitotic CDK1/cyclin B1 complex, these results may implicate RGC-32 upregulation in EBV-mediated tumourigenesis." (PMID 22163048, 2011). "cyclin B1, which regulates the G2/M transition in cell cycle progression, mitosis, apoptosis, checkpoint controls, growth and maturation, and is up-regulated in diverse cancers, 2)." (PMID 22053823, 2011). "In cancer cells, cyclin B1 expression has also been detected in G1 phase." (PMID 19293801, 2009). "CCNB1, another key component in cell cycle control, has a role in G2/M progression, acting with CDK1 to control chromosome condensation; it has been implicated in tumourigenesis and in metastasis in different cancers." (PMID 19753302, 2009). "Overexpression of Ccnb1 was also observed in lung and gastrointestinal cancer." (PMID 19032793, 2008). "Inhibiting cyclin B1 function in combination with chemotherapeutic drugs could reinforce the antiproliferative effect in a subset of cancers." (PMID 19113992, 2008). "Oncogenes such as MYC, AKT1, AKT2, cyclins CCNA2, CCNB1, CCNB2, CCNE1, CCNE2 and cyclin-dependent kinases CDK1 and CDK4, which were upregulated under androgen treatment, exhibited a significantly reduced expression following PVT1 knockdown, thereby modulating cancer-associated oncogenic pathways." (PMID 41792045, 2026). "The two most highly upregulated genes were MTDH, which encodes for the transmembrane protein metadherin that is involved in multiple aspects of cancer progression, metastasis, and drug resistance, and cyclin B1 (CCNB1), suggesting that cell cycle inhibitors may be effective against these cells." (PMID 38999963, 2024). "The results demonstrated that CCNB1 alterations were present in 1.3% (140/10950) of pan-cancer patients, indicating that CCNB1 genetic alterations could play a role in promoting cancer progression." (PMID 38581717, 2024). "However, the majority of studies on CCNB1 have been limited to specific types of cancer." (PMID 38581717, 2024). "Therefore, our objective is to systematically characterize the role of CCNB1 in pan-cancer." (PMID 38581717, 2024). "Thus, use of SCCAg and CCNB1 biomarkers for distinguishing early-staged cancers from benign masses could be of great value." (PMID 36287252, 2023). "Variations in the anti-mitotic activity and disruption of MT dynamics in numerous cancer cell types have been observed due to differences in the chemical carbocyclic structure of SLs, all of which trigger G2/M arrest via the upregulation of p-Cdk1 (Try 15) and cyclin B1." (PMID 35651747, 2022). "Indeed, CAP-treated cancer cells showed G2/M arrest with decreased cyclin B1." (PMID 32604902, 2020). "CCNB1, CKS2, MKI67, RRM2, TK1 and TOP2A were found with positive clinical correlation to GLEASON SCORE, and we could clearly identify the core factors as cancer risk factors, the expression level increased as Gleason score elevated." (PMID 32266115, 2020). "The occurrence, development, and treatment of cancer may also be related to cyclin B1." (PMID 26786409, 2016). "Thus, targeting USP22 might be an effective and convenient approach to treat cancers with high levels of CCNB1 expression." (PMID 27030811, 2015). "Furthermore, it has been revealed that cell cyle factors such as cyclin D1 and cyclin B1 was downregulated by ZFX knockdown in multiple cancer types, which might account for the cell cycle disruption in Tca-8113 cells treated with ZFX-siRNA." (PMID 25916205, 2015).
cancer (continued). "In parallel to Cdk inhibitors, which have been extensively under clinical investigations, small molecule inhibitors against cyclin B1 could open up a new door for specific molecular cancer therapy by interfering with its protein stability, binding capacity to Cdk1 or its subcellular localization." (PMID 19113992, 2008). "CCNB1, PLK1, CDK1, BUB1B, AURKA, and NDC80 are genes involved in various stages of the cell cycle process, which is crucial from a cancer perspective." (PMID 40287845, 2025). "CCT4 expression was positively correlated with oncogenic proteins involved in cell proliferation and survival, including PCNA, Cyclin B1, FOXM1, across multiple cancer types." (PMID 41403933, 2025). "The occurrence of abnormal mitosis, which is triggered by the CCNB1/CDK1 complex, plays a significant role in the genesis and progression of cancer." (PMID 40198519, 2025). "AOH1160 repressed the expression of CDK1, CCNB1, CDK2 and CCNE2 to arrest the cell cycle at G2/M phase, thus blocking the promotion of cancer cell mitosis." (PMID 40313621, 2025). "We detected that green tea extract enables the inhibition of cell proliferation through suppression of cyclin B1 and CDK1 expression (or CDK1 activity) in PC3 cancer cells." (PMID 40336533, 2025). "RO-3306, a selective small-molecule inhibitor of CCNB1/CDK1, has been widely used in cancer-related research." (PMID 40430484, 2025). "We also found that cyclin B1 and CDK1 expression (or CDK1 activity) was inhibited by green tea extract in PC3 cancer cells." (PMID 40336533, 2025). "For example, the cell cycle protein Cyclin B1, which plays a key role in the progression of the cell cycle, has been identified as TAA in several cancers." (PMID 40533767, 2025). "Western blot experiments confirmed the reduced expression of CDK1, CCNB1, and PLK1 in KIF2C knockdown cancer cells at the protein level." (PMID 41333555, 2025). "Specifically, CCNB1 is known to facilitate cell cycle control and DNA synthesis in HCC, enhancing the proliferation of cancer cells." (PMID 39822992, 2025). "After GluOC treatment, cyclin A2, cyclin B1 and CDK1 increased, while Y-27632 suppressed cell cycle progression in cancer cells." (PMID 39054484, 2024). "Consistent with the microtubule‐targeting activity of VU‐0365114, cancer cells with higher levels of mitotic regulators (CDK1, CCNB1, and STMN1) were more sensitive to VU‐0365114." (PMID 37842807, 2024). "CKS2 can increase cyclin, cyclin A, cyclin B1 and CDK1, thereby promoting cancer cell proliferation." (PMID 39188686, 2024). "Accumulating evidence suggests that CKS2 is an oncoprotein that promotes cancer tumorigenicity and progression, and that CKS2 levels in PTC correlate with the expression of its downstream genes, including cyclin B1 and CDK1." (PMID 39188686, 2024). "The expression of certain cell cycle genes (CCNB1, CCNE1, CCNE2, and FOXM1) was race-dependent in several cancer types and correlated with significant survival differences." (PMID 37345032, 2023). "To understand the regulatory mechanism of FOXM1a in cancer cell proliferation and tumorigenesis, we analyzed the effects of FOXM1a on the expression of FOXM1c target genes, including CDC25B, PLK1, and CCNB1, which are essential for cell proliferation." (PMID 37759731, 2023). "Using Timer 2.0, we found that PLK1, CDK1, CCNB1, and CCNB2 were upregulated in different cancer types compared with normal samples from the TCGA data set." (PMID 37007025, 2023). "CXCR2 activation also reduces the expression of p21 and increases the expression of cyclins and cyclin dependent kinases such as cyclin A, cyclin B1, cyclin D1, cyclin E, CDK2, and CDK6, thereby promoting the increased proliferation of cancer cells." (PMID 37686093, 2023). "mmp1 promotes cell cycle acceleration in cancer cells by activating the cdc25a/CDK4-cyclin D1 and p21/cdc2-cyclin B1 complexes." (PMID 36225568, 2022). "Thus, decreasing the levels of cyclin B1 could be a potential approach for treating cancer." (PMID 36431014, 2022).
cancer (continued). "At present, many studies have shown that the hub genes CDC20, CDK1, BUB1, CCNB1, and BUB1B identified in our PPI network are involved in cancer progression." (PMID 35664322, 2022). "By analysing the TCGA database, we found that CCNB1, CDC25C, CENPM, and EXO1 were highly expressed in almost all of the 33 cancers, and we also noticed significant high expression in LUAD." (PMID 35646074, 2022). "As expected, most genes in the cytotoxicity group were involved in cell cycle regulation, such as CCNB1 and WEE1, or are components in the ubiquitin–proteasome system (UPS), such as UBC and UBB, which are known to be active in cancer cells." (PMID 35459228, 2022). "The expression of p21, CDK1 and cyclin B1 was shown to be altered in BAP31 knockdown cells, suggesting that regulation on cell cycle distribution contributed to BAP31 participated cancer cell migration." (PMID 35359416, 2022). "Univariate Cox regression analysis identified four genes (CCNB1, CCNA2, IL1A, and MMP3) that significantly affected patient survival based on the 27 anticolon cancer targets of THCQF." (PMID 35479514, 2022). "The expression of lncRNA DEPDC-AS1, CCNB1 and CDC20 in carcinoma of urinary bladder cell line was determined by qRT-PCR analysis." (PMID 35280820, 2022). "LncRNA DEPDC-AS1 as well as CCNB1 and CDC20 had significantly higher expressions in carcinoma of urinary bladder tissues compared to normal paracancerous tissues." (PMID 35280820, 2022). "In the present study, Western blotting showed that cyclin B1 was attenuated by the downregulation of YBX-1 in HCT116, SUIT2 and OE33 cells, suggesting that YBX-1 also regulates the cell mitotic events in cancer cells." (PMID 34202873, 2021). "TA had no consistent effect on ERK or AKT phosphorylation, Cyclin D1 or Cyclin B1 levels, or PARP or Caspase 3 cleavage across the MDA-MB-468, BT474, and WM793 human cancer cell lines." (PMID 35095503, 2021). "In this subtype, FOXM1, TOP2A, CCNB1, CCNB2, and CDC25A participate in DNA repair and are activated during disease relapse or play a role in the prognosis of other cancers, thereby supporting the poor prognostic characteristics of the DP.BCG+ subtype." (PMID 33535616, 2021). "The upregulated of cyclin B1, cyclin B2, and CDK4 indicated the radiation treatment stimulates the subpopulation of cancer-stem-like cells cell cycle progression and proliferation." (PMID 33931075, 2021). "Matrine arrests the cell cycle and induces apoptosis in several cancer cell lines, and the mechanism is downregulated cell cycle-related proteins CDK1, Cyclin B1 and Cyclin D1." (PMID 34809653, 2021). "Western blotting showed that cyclin B1 was decreased by the downregulation of UPF1 in HCT116, SUIT-2 and OE33 cells, suggesting that abnormal cell division occurred in UPF1-downregulated cancer cells." (PMID 34202873, 2021). "Western blotting showed that the expression of cyclin B1 and cyclin D1 was decreased by the downregulation of EIF3G, suggesting that the cell cycle and mitotic events are controlled by EIF3G in cancer cells." (PMID 34202873, 2021). "Among all cyclin genes analyzed, CCNA2, CCNE2, CCNB2, CCNB1, CCNF, and CCNE1 were most elevated in the included cancers." (PMID 33996604, 2021). "For example, studies have found that the downregulated expression of circRNA circ-Ccnb1 in breast cancer can interact with Bclaf1 in cancer cells through H2AX, resulting in the inhibition of uncontrolled division and growth of cancer cells." (PMID 33884267, 2021). "The authors suggest that circCCNB1 forms a complex with CCNB1 and CDK1, thereby preventing their translocation to the nucleus and suppressing the proliferation and survival of cancer cells." (PMID 33466455, 2021). "We found that FDI-6 and FOXM1 shRNA impaired Olaparib-induced expression of CDK1, CCNA1, CCNB1, and CDC25B to inhibit the mitosis of cancer cells." (PMID 34880209, 2021).
cancer (continued). "In particular, FOXM1 regulation of cell cycle and mitotic genes, such as CCNB1, CDK1, and CENFP, is conserved across different cancer types." (PMID 34205406, 2021). "The subgroups include proliferation genes (Ki67, STK15; Survivin, CCNB1, MYBL2), invasion genes (MMPP11, CTSL2), HER2 genes (GRB2, HER2), estrogen genes (ER, PGR, BCL2, SCUBE2), and other cancer related genes (GSTM1, CD68, BAG1)." (PMID 33665165, 2020). "Several genes, including CCNB1, CDC20, CDC6, PLK1, and PTTG1, had multiple roles as core essential genes, oncogenes, and roles as hallmarks of cancer and in KEGG pathways." (PMID 32040444, 2020). "Nocodazole, a prototypic microtubule inhibitor, can cause G2/M cell cycle arrest and results in strong up-regulation of cyclin B1 and CDK1 levels in human cancer cells." (PMID 32181475, 2020). "For example, we observe that PLK1, CCNB1/2, CCNA2, AURKB and BUB1B are shared across 6–9 cancer types and physically interact with several deregulated neighbouring genes in our activated modules." (PMID 31396397, 2019). "Both CCNB1 and TERT consistently showed higher expression levels in cancer tissues of three types than in normal tissues." (PMID 31856825, 2019). "As for the relationship between anticancer drugs and hub genes, we found CCNB1 and CDK1 were the targets of cancer drugs." (PMID 31134129, 2019). "Accumulating studies have demonstrated that several cell cycle–related genes such as CCNB1, CCNA2, and CDK1, which were also identified in the current study, are involved in the initiation and development of cancer." (PMID 31428132, 2019). "Here, we identified that expression of cyclin B1 and Cdk1, cell cycle regulatory proteins, are affected by GSK-3 inhibition in cancer cells." (PMID 31882719, 2019). "It is well known that CCNB1 triggers mitosis in the G2 phase to promote cell proliferation and tumorigenesis by phosphorylation and inhibition of FOXO1 in cancers after binding to CDK1 and initiating the kinase activity 17-19." (PMID 31592235, 2019). "Although APC/C serves as the E3 ligase for cyclin B1, genetic deletion of APC/C in Project Achilles showed that APC/C was an essential gene across all cancer cell lines." (PMID 30860482, 2019). "To examine the link between MELK and cell division in cancer, we compared the levels of MELK expression with five well-characterized proliferation markers: MKI67, PCNA, CCNB1, MCM2, and TOP2A." (PMID 29417930, 2018). "The expressions of Cyclin B1 and CDK1 displayed dramatically decreased levels in these cancer cell lines treated with Spiclomazine." (PMID 29467941, 2018). "Consistent with our results, quercetin treatment has been reported to increase cyclin B1 level and CDK1 kinase activity in cancer cells." (PMID 28418847, 2017). "In contrast, Cud C downregulated MYB1 (v-myb avian myeloblastosis viral oncogene homolog), CCNB1 (cyclin B1) and GPX2 (Glutathione peroxidase 2), which have been shown to promote cancer proliferation and metastasis." (PMID 28107519, 2017). "LOX knockdown leads to G2/M phase arrest; reduced p-H3(Ser10), cyclin B1, CDK1, and Aurora B. Moreover, LOX knockdown significantly increased sensitivity of cancer cells to chemotherapeutic agents that target microtubules." (PMID 27296552, 2016). "Both fc-rPEI-Cdots/cyclin B1+ EGFR and fc-rPEI-Cdots/cyclin B1 complexes showed anti-cancer effect in treatment period for 72 hrs." (PMID 26880047, 2016).
cancer (continued). "Here, we demonstrate that crosstalk between the two putative cancer stem cell genes, USP22 and CCNB1, has an important role in colorectal tumorigenesis." (PMID 27030811, 2015). "To date, only limited targets including miR-155, IRF5, Blimp1, CCNB1, BCL6, CDK6, Myc, and several others have been identified as IRF4 targets in cancers." (PMID 25207815, 2014). "In the present study PPP treatment resulted in prominent CDK1 activation with increased levels of Cyclin B1 protein and mRNA, increased Cyclin B1 in complex with CDK1, and CDK1Thr161 phosphorylation in cancer cell lines or tumors." (PMID 25268741, 2014). "Gene expression analysis showed that clonogenic side population cells in cancers express genes involved in the cell cycle and mitosis (e.g., SKA1, CCNB1, CDC25C, CDC2, BIRC5, CENPE, AURKB, KIFs, TOP2A, ASPM) more strongly than non-side population cells." (PMID 23962337, 2013). "Here we found several proliferation promoting genes including cyclin B1 /CCNB1/, cyclin E1 /CCNE1/ and cyclin-dependent kinase (CDK1) to be upregulated both in young and cancer samples compared to normal adult mucosa." (PMID 24098334, 2013). "We previously showed that cancer cells treated with DH166 exhibited elevated cyclin B1 protein levels, but the increase of cyclin B1 was obvious only when cells were treated with high concentrations of DH166 (about 10 fold of IC50)." (PMID 23056340, 2012). "In this study, we examined the effect of the silencing ofcancer-related genes by small interfering RNAs (siRNA) targeted atmRNAof Her2, cyclin B1(CCNB1), and protein kinase C(PKC) on theproliferation of human cancer cells of different origins." (PMID 22649691, 2011). "C-myc, cyclin A, cyclin B1, cyclin D1, CDK2, and survivin contributed to the separation between the cancer and non cancer groups." (PMID 20504322, 2010). "Current studies suggest that CCNB1, TTK, and CDC20 are overexpressed in various cancers." (PMID 40181976, 2025). "Additionally, HSP increased ROS generation and JNK1/2, p38, Bax, and p21 expression in A431 human cancer cells while suppressing ERK1/2, cyclin B1, D1, D3, and E1 expression, which resulted in apoptosis and decreased cell viability." (PMID 40427522, 2025). "These suppress the breakdown of cyclin B1 and CDK2 to stop the development of cancer." (PMID 40078339, 2025). "Furthermore, when ROS inhibited the phosphatase CCNB1, leading to the activation of CDK1, it promoted the cycle progression of cancer cells." (PMID 40183046, 2025). "Consistently, after LARP6 knockdown, western blot results also showed reduced expression of Cyclin B1 and CDK1, which drive the cell cycle progression from G2 to M phase, indicating that LARP6 promotes the proliferation of TNBC cancer cells via regulation of the cell cycle progression." (PMID 40635123, 2025). "Most notably, CCNB1 expression demonstrated the strongest positive correlation with CD4+ Th2 T cell, CD4+ Th1 T cell, and common lymphoid progenitor cells across various cancer types." (PMID 38581717, 2024). "The depletion of KIF18A showed a trend toward increased cyclin B1 (G2M marker) and cl-PARP (apoptosis marker) protein levels as well as decreased MCL-1 (a pro-survival marker) protein levels in those cancer cell lines sensitive to KIF18A KD in our cell growth assay." (PMID 38151625, 2024).